CD34 (CD34 molecule)
Diseases named in the same sentence as CD34 in open-access papers (continued):
Sharing a sentence is not in itself a finding about the gene and the disease.
cancer (continued). "Our results show that among the three VTRNA1s, VTRNA1-3 was the only gene silenced in cancer cells and also expressed in healthy donor CD34+ cells." (PMID 26473932, 2015). "CD34 is a known marker for endothelial cells and is expressed by cancer cells with neoangiogenetic potential." (PMID 26134824, 2015). "We co-stained for Meis1-EGFP with K14, K10, and cancer stem cell markers such as β4 integrin, CD34, and K15." (PMID 25013928, 2014). "CXCR4 is over-expressed in more than 20 different cancers, and expression in normal tissues (other than in the CD34 stem cell niche in bone marrow) is measurably lower." (PMID 24959420, 2014). "Expression of Beclin-1, PCNA, NET-1, Bcl-2, Bax, Survivin in cancer cells and CD34 in stromal microvessels were evaluated immunohistochemically in tissue microarrays comprising 103 cases of HCC and 57 matched adjacent nontumor liver tissues." (PMID 24885292, 2014). "Classically MSCs lack expression of CD34, but here we show that a small subpopulation of CD34+ cells can be isolated from KTOSA5 cells with characteristics of cancer stem cells." (PMID 24416158, 2014). "Intratumoral MVD was quantified by counting CD34-positive endothelial cells in cancer tissues, and the staining intensity of MVD ranged broadly from 12 to 118 microvessels/200×magnification field." (PMID 24523874, 2014). "The presence of CD34/CD133 double-positive cells was determined in cancer-adjacent and cancer tissues by flow cytometry." (PMID 24765203, 2014). "Cells were magnetically sorted for expression of the cancer stem cell marker, CD34 (data unpublished), and assayed for cell viability after treatment with either mavacoxib or carprofen." (PMID 25190452, 2014). "It was concluded that CD34+ cell-derived monocytes from cancer patients are able to present recall antigens and TAA to autologous T cells." (PMID 23180014, 2013). "The autologous T lymphocytes isolated from PB of cancer patients were added to CD34+ cell-derived CD14+ monocytes and preexposed to recall antigens, γ-irradiated HPC-4 cells, and TMVHPC." (PMID 23180014, 2013). "The use of BM CD34+ cells from cancer patients also led to the production of up to 60 % CD14+ monocytes containing these subsets, however, occurring at the ratio 1:1." (PMID 23180014, 2013). "With the use of these well recognized markers, it appeared that ATC tissue harbored only three types of cells: NOX2+ P22phox+ CD163+ CD68+ CD34− macrophages; NOX2− P22phox− CD163− CD68− CD34− cancer cells and NOX2− CD163− CD68− CD34+ blood vessel endothelium." (PMID 21811634, 2011). "Initially, we investigated the expression of the cancer stem cell markers Cd34, Cd24a, Cd44, Cd133, Cd90, Podoplanin (Pdpn), Nestin (Nes) and Discs, large homolog 7 (Drosophila) (Dlg7)." (PMID 21152443, 2010). "Our culture system exemplifies a major breakthrough in producing pure NK cell products from limited numbers of CD34+ cells for cancer immunotherapy." (PMID 20169160, 2010). "Although graft manipulation differed between cancer patients (un-manipulated) and RA (CD34 selected ± T-cell depletion) we found that graft manipulation did not affect the rate of reconstitution in RA patients (data not shown)." (PMID 15642146, 2005). "A clinical trial involving transduction of G156A MGMT into CD34+ cells of patients with cancer has been approved." (PMID 14562026, 2003). "The frequency of CD34+ cells in the blood of cancer patients was significantly higher than in control subjects (1.13±0.32%, n=7 vs 0.57±0.06, n=12; P=0.041)." (PMID 14562018, 2003). "Sections (4 microm) from these carcinomas were labelled for endothelial cells using anti-CD34, and the vessel counts were compared with the radiological grades." (PMID 9218730, 1997). "Thus, cancer cachexic CD45+ EPC induced CD34+ progenitor cell death and consequently decreased thymocytes, which finally contributed to the maturation disorder of mFbs." (PMID 40665793, 2025).
cancer (continued). "We found that cancer.cell. communicated with CD8_ANXA1, Mono_EREG, CAF_C3, and Fibrocyte_CD34, which further identified that cancer.cell. might be an immune-escaped cell cluster." (PMID 40725006, 2025). "Additionally, we compared the differences in CAPG expression between normal and cancer cell lines and found that both mRNA and protein levels of CAPG in cancer cell lines were higher than in CD34+ HSPC." (PMID 38700746, 2025). "The interaction with CD34, a hematopoietic stem cell marker, could be relevant in the context of cancer stem cells (CSC)." (PMID 40650074, 2025). "Additionally, the percentage of CD34+ cancer stem cells was decreased in the peripheral blood of the mice of PKMYT1‐knockdown group." (PMID 40279509, 2025). "Additionally, the oncogene MYC, associated with various cancer types, influences drug sensitivity in CML and aids in the survival of CML CD34+ leukemic stem cells." (PMID 38607055, 2024). "Direct IL-33 injection into cancer patients, generation of human immunogenic cDC1s from CD34+ hematopoietic progenitor cells using IL-33-derived factors, and development of highly immunogenic human Mo-DCs using IL-33-induced factors from human PBMCs are proposed strategies." (PMID 38825642, 2024). "In this study, only a few stemness genes, such as SOX2, TWIST1, and CD34, were aberrantly expressed [absolute fold change (FC) ≥ 2] in more than five cancer types, indicating that integrins may function downstream of key stemness factors." (PMID 39436262, 2024). "There is little information on CD34+DNAM-1brightCXCR4+ Inflammatory precursor entry in inflamed tissues and particularly into cancer tissue, while trafficking and developmental trajectory towards secondary lymphoid organs or thymus of conventional CD34+DNAM-1-CXCR4+ cells is well characterized." (PMID 38390333, 2024). "Furthermore, GAS5 upregulation is shown to inhibit telomerase activity in cancer cells and decreases proliferative potential of cord blood CD34+ cells compromising haematopoietic colony formation in vitro." (PMID 39198715, 2024). "CD34 and D2–40 staining verified carcinoma invasion in the cervical stromal lymph vascular space." (PMID 39411132, 2024). "The cells were further annotated as specific cell type subpopulations according to the expression of classic markers, including T cells (CD3D+), myeloid cells (CD68+), endothelial cells (CD34+), hepatocytes (ALB+), B cells (CD79A+), and cancer-associated fibroblasts (CAFs) (ACTA2+)." (PMID 37383234, 2023). "It is speculated that CD34+ cells, which are known to be endothelial progenitors, may play a role in angiogenesis and contribute to cancer stemness and metastasis in the context of CSCs." (PMID 37241170, 2023). "Their study provides valuable insights into the molecular mechanisms underlying tumorigenesis and may have implications for the development of new cancer therapies targeting CD34 or related pathways." (PMID 37241170, 2023). "This could lead to the development of new targeted therapies that can disrupt the role of CD34 in promoting cancer growth and progression, ultimately improving the prognosis for individuals with cancer." (PMID 37241170, 2023). "CD34+ /S100- DFSP cancers were evident in most of the DFSP cases." (PMID 37829962, 2023). "There may also be connections to protein serotonylation through aspects of cancer immunotherapy via alterations in CD34 structural modifications through serotonylation." (PMID 36831672, 2023). "This could explain the difference or preference of cancer cells to MSCs and migrasome network over CD34+ HSPCs." (PMID 36788616, 2023). "During wounding or invasion of cancer cells, such CD34+ stromal cells may transdifferentiate into ACTA2+ myofibroblasts." (PMID 37190121, 2023). "CD34 is commonly used as a marker to identify and isolate CSCs in various types of cancer." (PMID 37241170, 2023).
cancer (continued). "Cell membrane dynamics between the cancer cells, i.e. KG-1a, and CD34+ HSPCs might also differ, as illustrated by the differential potential to form tunneling nanotubes." (PMID 36788616, 2023). "However, autologous modeling requires isolation of CD34+ cells from cancer patients through invasive procedures such as bone marrow biopsies and leukapheresis, which are not routinely feasible." (PMID 36212401, 2022). "Interestingly, FLRT2 was expressed abundantly in CD34+ endothelial cells within areas of progression in stage IV cancer samples, but far less so in superficial areas." (PMID 35104247, 2022). "A comprehensive understanding of the molecular mechanisms subtending CD34+ cell-mediated neovascularization may provide novel therapeutic strategies in cancer treatment." (PMID 36611906, 2022). "Similarly, in AML patient samples, anti-VISTA-antibody on IgG4-Pro backbone, but not on IgG1-KO backbone, increased interactions, as a novel readout of activity, between immune cells and CD34+ AML cancer cells." (PMID 35967294, 2022). "Importantly, DJ34 significantly reduced the relative number of CD34+ CD38− LSCs in the total pool of bone marrow–derived cancer cells, showing that LSCs are particularly sensitive to DJ34." (PMID 33303632, 2021). "The use of CD34 for the prognosis, diagnosis, and treatment of various cancers has been increasing." (PMID 31968004, 2020). "Since eurochevalierine exerts its anti-cancer activity as a cytostatic agent, we further tested the impact of this natural compound on a proliferating healthy cell model represented by primary human CD34+ stem/progenitor cells." (PMID 29401749, 2018). "The higher MVD/CD34 values in the T1–T2 compared to T3–T4 cancers are counterintuitive and suggest that the current practice of using CD34 as a marker of MVD may be questioned." (PMID 29748768, 2018). "Importantly, eurochevalierine targets preferentially cancer cell proliferation (selectivity factor ≫ 7), as normal human primary CD34+ stem/progenitor cells were less affected by the treatment." (PMID 29401749, 2018). "Interestingly, the level of miR-25-3p (red) in CRC cells (labeled by CK, purple) positively correlated with that in cancer-adjacent endothelial cells (labeled by CD34, green)." (PMID 30568162, 2018). "CD34 is a surface marker for stem cells and cancer stem cells in the skin." (PMID 29081891, 2017). "We sorted CD34+ cancer stem cells from K14Cre;TRF2f/f;Terc-/- and control SCC by flow cytometry." (PMID 29113290, 2017). "The results suggested that DADS downregulated LIMK1 expression to decrease the expression of vimentin, CD34, and Ki-67; increase E-cadherin expression; and impede cancer cell proliferation, angiogenesis, and EMT alteration, thereby inhibiting invasion and metastasis." (PMID 28358024, 2017). "However these cells comprised a small fraction of total cells in the tumors, and as few as 103 CD34-Lgr6- basal cells formed cancers when serially transplanted suggesting that additional tumorigenic populations were present in these cancers." (PMID 29113290, 2017). "The results suggested that DADS could downregulate the expression of LIMK1 to impair the expression of vimentin, CD34, and Ki-67 and increase the expression of E-cadherin, thereby inhibiting cancer growth, invasion, and metastasis." (PMID 28358024, 2017). "Restoration of Tgfbr2 in Tgfbr2 cKO CD34+ SCCs dramatically reduced the frequency of mCherry+CD34+ CSCs from 6.5% to 2.5%, demonstrating that loss of TGFβ signaling is a requirement for CSC maintenance in transition zone carcinoma." (PMID 28219480, 2017). "Interestingly, some cancer stem cell (CSC) associated transcripts, such as CD117, CD34, Oct-4, CD44, ALDHA2 and Nanog, were down regulated in the A549 and PG cells expressing miR-708-5p." (PMID 26678031, 2016). "Higher USE scores in malignant tumors might reflect a higher portion of MFS with acquisition of smooth muscle actin and a loss of CD34 expression." (PMID 26846996, 2016).
cancer (continued). "Blood vessels in cancer tissues were detected and analyzed using the CD34 antibody." (PMID 26013572, 2015). "Consequently, autologous CD34+ stem cells can be administered therapeutically to cancer patients following radiation-dependent bone marrow ablation, thereby successfully transplanting an entire cancer-free hematopoetic lineage." (PMID 27087761, 2015). "In addition, we find that VTRNA1-3 is silenced by DNA methylation in a human leukemia cell line, but unmethylated in CD34+ HSCs from healthy controls, indicating cancer-specific silencing." (PMID 26473932, 2015). "As is the case with the SFDM sphere-induced tumors, these tumors were positive for CD44, vimentin, laminin and diffusely positive for CD31 and CD34 staining, suggesting that the anti-miR-17 cancer sphere cells were able to recapitulate both renal and endothelial cell types of RCC." (PMID 25011053, 2015). "Cancer tissue CD34, CD133 and VEGFR-2 mRNA levels were determined by qPCR." (PMID 24765203, 2014). "Y-27632 has been shown to have contrasting biological effects in different systems, ranging from pro-proliferative effects on hESCs and hiPSCs to anti-proliferative effects on cancer cells, cord blood-derived CD34+ hematopoietic progenitor cells, hepatic stellate cells and smooth muscle cells." (PMID 25337699, 2014). "However, we wish to suggest that in general, BM CD34+ cell-derived monocytes of cancer patients possess a higher cytotoxic/cytostatic activity, around 40 %, while such monocytes generated from CB around 20 %." (PMID 23180014, 2013). "The question may arise, whether monocytes obtained from BM-derived CD34+ cells of healthy donors behave differently or in the same way as those from cancer patients." (PMID 23180014, 2013). "Also, CB-PIC suppressed in vivo growth of SW620 cancer cells, and IHC showed decreased expression of Ki-67, CD34, and CAIX and increased expression of pAMPKα." (PMID 23589723, 2013). "Among them, Cd34, protein tyrosine phosphatase, receptor type, F (Ptprf), Txnrd1, Pgd, Ugt1a1, Gpr137b, and dynein light chain Tctex-type 1 (Dynlt1) were connected in a molecular network of cancer-cell cycle-cell death." (PMID 22039513, 2011). "In addition to it’s expression in cancer and cancer stem cells, in AML hTERT levels have been found to be associated with CD34 expression and chromosomal abnormalities (P = 0.01 and P = 0.001, respectively)." (PMID 19662193, 2007). "Several genes and signaling pathways not previously associated with ex vivo expansion of CD133+/CD34+ cells were identified, most of which associated with cancer." (PMID 17559657, 2007). "Moreover, we exploited a CIBERSORTx digital flow cytometric analysis of NSCLC RNA-Seq bulk tumors, and we identified that immune (CD45+), epithelial/cancer (EpCAM), and stromal (CD10+ and CD34+) subsets were expressed in NSCLC and associated with poor prognoses." (PMID 37509650, 2023). "While the CD166 homotypic interactions can play a role in the adhesion of hematopoietic cells to migrasomes, the difference in the absorption of migrasomes observed between KG-1a cancer cells and CD34+ HSPCs might be a result, among others, of additional proteins that interact with CD166." (PMID 36788616, 2023). "ob-aT bASCs exhibited an increased ability to stimulate cancer stemness in highly malignant MDA-MB-231 cells by enhancing the gene expression of pluripotency and CSC associated genes such as ALDH1H1, ALDH2, c-MYC, CD34, LGR5, CXCR4, SOX2 and OCT4, fueling further their malignant potential." (PMID 36710348, 2023).
cancer (continued). "Additionally, CD34+ is also expressed in some cancer stem cells." (PMID 35565356, 2022). "CD34+SCs/TCs are not observed in the stroma of numerous malignant invasive epithelial tumours, where they are replaced by αSMA+ stromal cells (myofibroblasts, cancer-associated fibroblasts: CAFs)." (PMID 33916213, 2021). "In addition to CD34, α6β1-integrin represents another marker for cancer-initiating cells." (PMID 33123267, 2020). "Podocalyxin (PCLP1), also known as podocalyxin-like protein 1, PODXL, PCLP, PC, or Gp135, is a CD34-related sialomucin expressed in renal podocytes, vascular endothelia, platelets, a subset of neurons, haematopoietic progenitors, embryonic stem cells and various types of cancer." (PMID 29245936, 2017). "Therefore, the MAGE C1+/CD34+ cells found in both the BM and PB of MM patients indicates that the primary malignant cell is not confined to the BM and that migration between these two sights allows for the spread of this cancer." (PMID 25793710, 2015). "Furthermore, we analyzed TLR7 and TLR8 in dissociated cells derived from the same patient tissues together with CD34, a marker for endothelial cells and known to be expressed by cancer cells with neoangiogenetic potential, by FACS and immunohistochemical analysis (cytospins)." (PMID 26134824, 2015). "The pharmacokinetics of subcutaneous G-CSF in healthy donors and cancer patients show a maximum serum concentration within 2 ± 8 h, and due to the short elimination half-life of G-CSF (approximately 3 ± 4 h), thus a twice-daily schedule may improve CD34+cell yield." (PMID 39954328, 2025). "Quantitative polymerase chain reaction (qPCR) revealed that the transcription level of MIR31HG, as well as three stem cell specific markers (CD133, CD34, and CD44) were significantly higher in cancer stem cell types than in parental cells." (PMID 37950038, 2024). "The aim of this study was to analyze the correlation of POSTN expression (in cancer cells and CAFs) with pro-angiogenic factors (CD31, CD34, CD105, and VEGF-A) in patients with NSCLC." (PMID 39272978, 2024). "Studies on cancer neovascularization often use immunohistochemical EC markers (CD31, CD34, CD105) to identify newly formed microvessels in diseased tissues (in this case, NSCLC)." (PMID 39272978, 2024). "Our results evidenced that the expression of cancer stem cell surface markers, including EPCAM, CSF3R, CD34, CD96 and ENG, were significantly different." (PMID 38977778, 2024). "DFSP cancers were detected and confirmed as myxoid DFSP based on the histopathological features and CD34+ S100- immunostaining." (PMID 37829962, 2023). "Furthermore, CD34 expression may also be found on a variety of cancer stem cells." (PMID 37241170, 2023). "Moreover, the presence of CD34 markers on CSCs may interfere with conventional cancer treatments." (PMID 37241170, 2023). "Heatmaps were utilized to compare the expression profiles of imputed and ground truth data for immune (CD45+), epithelial/cancer (EpCAM), and stromal (CD10+ and CD34+) subsets." (PMID 37509650, 2023). "CD34+KIT low stem cells for GIST, cancer cell quiescence, and altering the metabolic phenotype of GIST through reactive oxygen species (ROS0 and hypoxia-inducible factor-1α (HIF-1α) can play a role 54–56." (PMID 37545902, 2023). "To assess anti-GDF-15 treatment against human cancer in vivo, we reconstituted NOD/SCID/γc-/-/FcγR-/- mice with human umbilical cord-derived CD34+ human hematopoietic stem cells." (PMID 37474523, 2023). "CD133 was first extracted from CD34+ hematopoietic stem cells using an anti-AC133 mAb and is specifically expressed in several cancers, including HCC." (PMID 35879685, 2022). "Through ultrasound imaging and CD34 immunohistochemistry staining, we previously confirmed that IRFA can promote angiogenesis in residual cancer." (PMID 35033089, 2022).